SOX2 (SRY-box transcription factor 2)
Diseases named in the same sentence as SOX2 in open-access papers (continued):
Sharing a sentence is not in itself a finding about the gene and the disease.
pancreatic cancer (continued). "In the present paper, we found a positive correlation between the protein expression of stemness markers (NANOG and SOX2) and IL20RB in pancreatic cancer samples, suggesting that IL20RB may promote tumor stemness." (PMID 38098005, 2023). "Next, to find out the underlying player(s) related to the change of cell stemness, we chose four major transcription factors that are commonly related to the stemness of pancreatic cancer cells, including KLF4, SOX2, Nanog and Oct4, to identify potential molecules for the regulation of the stemness." (PMID 37280198, 2023). "Notably, treating pancreatic cancer cells with Stattic, a STAT3 inhibitor, substantially reversed the upregulation of mRNA expression of tumor stemness markers (NANOG, SOX2 and POU5F1) induced by IL20RB overexpression." (PMID 38098005, 2023). "Together, these data strongly indicate that Sox2 expression in adult pancreatic epithelial cells is sufficient to drive alterations in lineage fate decisions, specifically initiating ADM and hyperproliferation, both early markers of pancreatic cancer." (PMID 35618699, 2022). "Further, positive identification of SOX2, SOX10 and TGFβ indicated presence of cancer stem cells in tumor organoids which might have some role in resistance to therapies in pancreatic cancer." (PMID 36713532, 2022). "Though studies have already shown that SOX2 induction by FGF and FGFR2 activation inhibits osteoblast differentiation, we propose that FGFR inhibition can also be an effective scheme for indirect inhibition of SOX2 in pancreatic cancer." (PMID 32457900, 2020). "Bitter melon water extract could inhibit CD44+/CD24+/EpCAMhigh CSC populations, decrease CSC markers SOX2, OCT4, NANOG and CD44 and enhance gemcitabine sensitivity in pancreatic cancer models." (PMID 32726914, 2020). "Though the regulation of FGF2 and FGFR2 on SOX2 has been already reported in the development phase, we were the first to demonstrate that FGFR signaling regulates the protein stability of SOX2 through AKT and promotes its nuclear localization, thus enhancing stemness in pancreatic cancer." (PMID 32457900, 2020). "In the pancreatic cancer cell lines AsPC-1 and PANC-1, miR-1181 decreases stem markers and pluripotent gene expression, suppresses tumorsphere formation, and shrinks the CSC population by inhibiting SOX2 and STAT3 expression." (PMID 31861404, 2019). "VEDT inhibited pluripotency transcription factors such as Nanog, Oct4, and Sox-2, Notch-1 receptor, metastasis marker MMP9 as well as Kras downstream signaling factors pAKT and pERK in pancreatic CSCs, indicating Kras signaling in pancreatic cancer stemness." (PMID 28404939, 2017). "In this study, we find that LIN28A increases the expression of stem cell markers SOX2, OCT4, LIN28B, c-Myc and NANOG in pancreatic cancer cells, and promotes their malignant behaviors including growth and invasion in vitro, further supporting the oncogenic potential of LIN28A." (PMID 26910839, 2016). "Additionally, CDKN1A was induced by SOX2 siRNAs in the presence of cycloheximide, suggesting the direct suppression of CDKN1A by SOX2, as has been reported in pancreatic cancer cells." (PMID 26846300, 2016). "The downregulation of SOX2 by 6-MITC and I7557 in PANC-1 pancreatic cancer cells harboring mutant K-ras may shed light on elucidating the interaction between SOX2, EGFR, and its downstream KRAS/BRAF and PI3K/AKT pathways." (PMID 24575144, 2014). "However, most of these studies have focused on the role of SOX2 in tumor stemness and a novel signaling axis, especially in pancreatic cancer, has not been studied in depth." (PMID 38164286, 2024). "In pancreatic cancer, there is no study related to SOX2 immune infiltration." (PMID 38164286, 2024).
pancreatic cancer (continued). "Furthermore, CD44V3 knockdown significantly suppressed the expression of multiple stemness markers, including BMI1, KLF4, SOX2, and NANOG, indicating that, in accordance with CD44V, CD44V3 possesses stemness-maintaining ability and then promotes pancreatic cancer migration and invasion." (PMID 36292918, 2022).
osteosarcoma (88 papers, 2011 to 2026). A usually aggressive malignant bone-forming mesenchymal neoplasm, predominantly affecting adolescents and young adults. "In a three-dimensional osteosarcoma model, the increased expression of several drug-resistance-related genes (Bcl2, Abcb1, Abcg2, Nanog, Sox2) was closely associated with heightened glutamine metabolism." (PMID 41300631, 2025). "Another protein associated with a CSC phenotype in osteosarcoma is SOX2 which was shown to maintain this cell population via modulation of the Hippo pathway." (PMID 33799834, 2021). "SOX2 was linked to enhanced tumorigenicity in pediatric sarcomas, and it was highly expressed in human and murine osteosarcomas." (PMID 30517668, 2020). "Up-regulation of MDR1 has been associated with chemo-resistance development of osteosarcoma tumor-initiating cells, and SOX2 mRNA, a marker of cancer stem cells, was up-regulated in our DOXO-resistant line." (PMID 31319571, 2019). "The loss of downregulation of SOX2 expression prevents the formation of osteosarcoma spheres." (PMID 39547513, 2024). "Significantly, this study provides the first evidence that SOX2 undergoes liquid-liquid phase separation (LLPS) in osteosarcoma, a critical mechanism for maintaining cancer stemness." (PMID 41824786, 2026). "In summary, we have elucidated the crucial role of AKT in promoting SOX2 overexpression, enhancing tumor stemness, and conferring chemoresistance in osteosarcoma (OS)." (PMID 39994220, 2025). "This study is the first to report that SOX2 indirectly participates in cholesterol metabolism in osteosarcoma cells by transcriptionally regulating LPCAT1." (PMID 41358198, 2025). "Collectively, our results demonstrated that DUSP3 regulates the stemness of osteosarcoma cells through the EGFR/STAT3/SOX2 axis." (PMID 39744427, 2025). "Inhibition of the STAT3/SOX2 signaling axis dramatically reduced the DUSP3 downregulation-promoting effects on osteosarcoma cell proliferation, migration, and invasion." (PMID 39744427, 2025). "In this study, we identified AKT as a critical oncogenic kinase responsible for the aberrant overexpression of SOX2 in osteosarcoma (OS)." (PMID 39994220, 2025). "The WAC-AS1 protein binds to miR-5047 and increases SOX2 expression to promote osteosarcoma cell proliferation and stemness." (PMID 39744427, 2025). "To validate the inhibitory effect of the AKT inhibitor on SOX2 protein levels, we treated SOX2-positive osteosarcoma (OS) cell lines, specifically HOS, with the AKT inhibitor MK2206 at varying concentrations for 24 h." (PMID 39994220, 2025). "This study provides compelling evidence establishing the SOX2/LPCAT1/cholesterol metabolism axis as a novel molecular mechanism driving osteosarcoma progression and metastasis." (PMID 41358198, 2025). "In conclusion, our study advances the understanding of osteosarcoma pathogenesis by identifying the SOX2/LPCAT1/cholesterol metabolism axis as a driver of tumor progression and metastasis." (PMID 41358198, 2025). "To determine the function of SOX2 in osteosarcoma, we validated the phenomenon in multiple OS cell lines in vitro using shRNA-mediated SOX2 knockdown (KD)." (PMID 39994220, 2025). "Western blots showed SOX2 expression and sphere formation capacity of osteosarcoma cells decreased after MK2206 addition." (PMID 39994220, 2025). "Our results showed that DUSP3 binds to EGFR, inhibiting its phosphorylation, thereby regulating STAT3/SOX2 axis and affecting osteosarcoma cell stemness." (PMID 39744427, 2025). "SOX2, a core transcription factor in pluripotency and stemness, is frequently overexpressed in cancers, including osteosarcoma, where it sustains tumor initiation, metastasis, and therapy resistance." (PMID 41358198, 2025). "The existing literature indicates that miR-5047 was a key negative regulator of osteosarcoma cell stemness and metastasis by target SOX2 mRNA." (PMID 39309008, 2024).
osteosarcoma (continued). "A recent study found that the deubiquitinase USP9X stabilizes the oncogene SOX2 protein expression through its deubiquitinating activity, and SOX2 mediates the promoting effect of USP9X on osteosarcoma cell proliferation." (PMID 39062505, 2024). "The same characteristics have been shown in osteosarcomas TICs, whereby SOX2 downregulation leads to tumorigenesis reduction in vitro." (PMID 39547513, 2024). "MIR-34a seems to be involved in the dedifferentiation of osteosarcoma via plasminogen activator inhibitor-1, whose inhibition suppressed the upregulation of SOX-2." (PMID 37176108, 2023). "A large enrichment of SOX2 was found in osteosarcoma stem cells, and by reducing SOX2 expression tumor cells can lose their tumorigenicity and regain their ability to differentiate cells." (PMID 37213675, 2023). "Some studies specifically investigated SOX-2 in osteosarcoma CSCs and its crosstalk with other signaling pathways." (PMID 37176108, 2023). "In fact, conditional knockout of SOX2 expression was demonstrated to drastically reduce the onset of tumor formation in a mouse model of osteosarcoma." (PMID 37176108, 2023). "SOX-2 has been the most well-studied embryonic transcription factor in osteosarcoma, with its role in tumor initiation and progression being well characterized." (PMID 37176108, 2023). "The protein levels of Sox-2, Oct3/4, and Nanog were inhibited by the treatment of levobupivacaine in osteosarcoma cells." (PMID 35333774, 2022). "The transcription factor Sox determining the region Y-box 2 (Sox2) plays a key role in developing and controlling the embryonic stem cell state and was identified as a biomarker for CSCs in osteosarcoma." (PMID 35582537, 2022). "Sox2 appeared essential for the survival and proliferation of all osteosarcoma cells, including CSCs." (PMID 35582537, 2022). "For example, the embryonal transcriptional regulator Oct-4, SOX2, and Nanog are previously found in osteosarcoma tissues and cells and play important roles in its development." (PMID 35333774, 2022). "MiR-34a was also found to be involved in the regulation of osteosarcoma dedifferentiation by acting via SOX2 downregulation." (PMID 35163570, 2022). "Western blot analysis was used to detect the protein levels of SP1, Wnt, β-catenin, c-Myc, and SOX2 in osteosarcoma cells." (PMID 35342417, 2022). "Our previous experimental studies indicate that established osteosarcoma cell lines possess an Aldefluor-positive cell fraction that are SOX2-positive but KLF4-negative, and further enriched in CSCs isolated from spherical colonies." (PMID 36232719, 2022). "Consistently, osteosarcoma tumor cells growing on 7 kPa substrate showed lower sensitivity to doxorubicin (Dox) compared to 20 kPa and 55 kPa substrate with elevated levels of Sox2, Oct4 and Nanog." (PMID 36419159, 2022). "Elevated SOX2 expression has been reported in many cancers, such as osteosarcoma, lung and esophageal squamous cell carcinoma." (PMID 33953166, 2021). "The expression of LIF was significantly higher in osteosarcoma cell lines and tumors and its expression levels were positively correlated to the stem cell core fators SOX2 and Nanog." (PMID 34198693, 2021). "Sox2 is known to bind the YAP promoter in osteoprogenitors as well as osteosarcoma cells, and can increase YAP activity in those cell types." (PMID 34201496, 2021). "They indicated that SOX2 inhibition by CRISPR-Cas9 in osteosarcoma cells decreases viability and proliferation of both CSC and non-CSC populations." (PMID 34768751, 2021). "The cooperation of YAP1 and SOX2 was detected in various cancer types, including osteosarcoma, urothelial cancer, and HNSCC (head and neck squamous cell carcinoma)." (PMID 35548450, 2021). "In osteosarcoma, the transcription factor SRY-Box Transcription Factor 2 (Sox2) was shown to counteract the Hippo pathway and to restrain its two activating components, WWC1 and neurofibromin 2 (NF2, merlin in Drosophila)." (PMID 33467643, 2021).
osteosarcoma (continued). "Others studies, however, showed that Sox2 antagonizes β-catenin signaling to maintain self-renewal in osteoblasts, mesenchymal stem cells, and osteosarcomas." (PMID 33302540, 2020). "LncRNA SOX2 overlapping transcript (SOX2-OT) was identified as an oncogene in osteosarcoma cells, regulating the migration, invasion, and expression of cancer stem cell biomarkers." (PMID 33117693, 2020). "SOX2 was further demonstrated to interfere with tumor-suppressive Hippo pathway to maintain CSCs in osteosarcomas." (PMID 30517668, 2020). "Previous research has shown that SOX2 maintains self-renewal of tumor initiating cells in osteosarcoma cell lines." (PMID 28934267, 2017). "Recently it has also been reported an oncogenic role of SOX2 by regulating osteosarcoma stem cells self-renewal." (PMID 28934267, 2017). "Immunoperoxidase staining in paraffin-embedded tumor tissues revealed the expression of SOX2 in all osteosarcoma tissues analyzed." (PMID 28934267, 2017). "Patient-derived tumor samples express different levels of SOX2, suggesting that the cancer stem cell population burden varies across osteosarcoma patients." (PMID 28934267, 2017). "We have previously verified that SOX2 is expressed in osteosarcoma tissue and cells directly isolated from patients." (PMID 28934267, 2017). "Osteosarcoma primary cells isolated after chemotherapy treatments (POST) express higher levels of SOX2 and OCT4 than cells isolated from the same patients (OS1 and OS6) before chemotherapy (PRE)." (PMID 28934267, 2017). "The levels of SOX2 expression in cells immediately after tumor tissue dissociation from eight different patients were accessed by Western blot and we found that osteosarcoma samples express different levels of SOX2." (PMID 28934267, 2017). "Here, we analyzed the levels of SOX2 expression in samples immediately after osteosarcoma tissue dissociation by immunohistochemistry, Western-blot, and immunofluorescence." (PMID 28934267, 2017). "We have previously shown that in murine osteosarcoma cell lines, Sox2 nuclear expression correlates with expression of the cell surface antigen Sca-1." (PMID 27528232, 2016). "Osteosarcomas contain undifferentiated tumor initiating cells or CSCs that express high levels of Sox2 are more efficient at inducing tumor formation and are believed to be responsible for relapse and reseeding of the disease." (PMID 27528232, 2016). "We have previously shown that Hippo signaling is repressed by SOX2 in osteosarcomas and these tumors have high YAP that is required for tumorigenesis." (PMID 27528232, 2016). "Low Wnt activity, high levels of PPARγ and low Hippo pathway activity characterize the CSC fraction of the osteosarcoma cell population, where high Sox2 expression antagonizes the Hippo pathway, represses the Wnt pathway and regulates PPARγ expression." (PMID 27528232, 2016). "The stem cell transcription factor, Sox2, is overexpressed in several mouse and human osteosarcoma cells as well as patient tumor samples, and its expression portends poor survival in patients." (PMID 27528232, 2016). "For instance, osteosarcomas and Ewing’s sarcomas express Oct4 and Nanog and rhabdomyosarcomas express Oct4, Nanog, and Sox2." (PMID 26412983, 2015). "Taken together, their data indicated that miR-126 functioned as a tumor suppressor in osteosarcoma, which exerted its activity by suppressing the expression of Sox2." (PMID 26194657, 2015). "Out of the differentially modulated genes, those implicated in stem cell and osteosarcoma biology, such as PPARG, ETS1, WNT1, WNT5B, SOX2, NANOG, POU5F1, nestin, and ALDH were chosen for further analysis." (PMID 22870217, 2012). "Therefore, the activation of AKT mediated by SOX2 likely plays a significant role in the development of resistance to DNA-damaging agents in osteosarcoma." (PMID 39994220, 2025).
osteosarcoma (continued). "Notably, elevated SOX2 expression has been reported to promote tumorigenesis and metastasis in osteosarcoma, while SOX2 inhibition can ameliorate these malignant phenotypes." (PMID 41358198, 2025). "The SOX2/LPCAT1 axis drives osteosarcoma progression by modulating cholesterol metabolism." (PMID 41358198, 2025). "SOX2 and LPCAT1 are implicated in tumor progression, but their roles in osteosarcoma pathogenesis and cholesterol metabolism remain unclear." (PMID 41358198, 2025). "While phosphorylation by various kinases has been demonstrated to stabilize SOX2 in multiple cancers, it remains unclear whether the aberrant overexpression of SOX2 in osteosarcoma (OS) is partially attributable to enhanced stability through phosphorylation." (PMID 39994220, 2025). "Targeting the EGFR/STAT3/SOX2 axis may be a promising therapeutic approach for treating osteosarcoma." (PMID 39744427, 2025). "While SOX2’s role in osteosarcoma is established, its impact on cholesterol metabolism via LPCAT1 remains unknown." (PMID 41358198, 2025). "Targeting DUSP3 and the EGFR/STAT3/SOX2 axis may offer a new therapeutic approach for treating osteosarcoma." (PMID 39744427, 2025). "The expression of PDK1 was significantly upregulated in 143B OSCs rather than in 143B non-OSCs, consistent with findings in the OSC population of primary osteosarcoma specimens, along with significant upregulation of stem cell markers, such as SOX2, KLF4, and ABCG1." (PMID 40730548, 2025). "The stem cell transcription factor Sox2 maintains cancer stem cells (CSCs) in osteosarcomas." (PMID 38607003, 2024). "Decitabine exposure in osteosarcoma reduces the protein expression of the metastasis-associated markers VIMENTIN, SLUG, ZEB1, and MMP9, with a concurrent decrease in mRNA expression of the known stem cell markers SOX2, OCT4, and NANOG." (PMID 37197432, 2023). "Likewise, in osteosarcoma, RNA-sequencing data suggested that SOX2 is underexpressed in 4SC-202-treated cells." (PMID 35406526, 2022). "Additionally, a mechanism by which the stemness of osteosarcoma cells dependent on the SOX2-YAP axis can be exploited to therapeutically induce adipogenesis has been proposed." (PMID 35119068, 2022). "Furthermore, osteosarcoma cells overexpressing EID3 had increased ability to grow in suspension as osteospheres with high expression of Sox2 and stem cell marker CD133." (PMID 36071872, 2022). "SOX2 balances the self-renewal of tumor-initiating cells in osteosarcoma." (PMID 34200614, 2021). "It was shown that SOX2 levels are regulated by Usp9x in osteosarcomas." (PMID 33613844, 2021). "The role of SOX2 in tumor initiation and progression has been well characterized in osteosarcoma." (PMID 32295077, 2020). "In sarcomas, SOX2 has been found overexpressed in CSCs from different subtypes and was described to play specific pro-tumorigenic roles in osteosarcoma." (PMID 32295077, 2020). "The pro-tumorigenic role of SOX2 has been particularly well described in osteosarcoma models." (PMID 32295077, 2020). "Besides osteosarcoma, clues for pro-stemness and/or pro-tumorigenic role for SOX2 has also been reported in Ewing sarcoma and embryonal rhabdomyosarcoma." (PMID 32295077, 2020). "Noticeably, TAED binding sites in SOX2 promoter identified here were different from those found in other reports whereby two putative YAP/TEAD binding sites were found at upstream (−3759) and downstream ( + 5313) of SOX2 transcription start site (TSS) in murine osteosarcoma cells." (PMID 31399556, 2019). "Furthermore, the protein expression of SOX2, which was reported to maintain the self-renewal of osteosarcoma-initiating cells, significantly decreased after dioscin treatment." (PMID 29497056, 2018). "miR-126 overexpression in osteosarcoma cells inhibited cell growth and invasion by targeting Sox2." (PMID 29113367, 2017).